CFD (complement factor D)
Diseases named in the same sentence as CFD in open-access papers (continued):
Sharing a sentence is not in itself a finding about the gene and the disease.
infection (9 papers, 2019 to 2024). The state of being infected such as from the introduction of a foreign agent such as serum, vaccine, antigenic substance or organism. "Since the CP and terminal pathway mediate the bacterial lysis, CFD inhibition potentially reduces the risk of infections compared with C5 blockade or even C3 blockade." (PMID 39416783, 2024). "As a complement factor, CFD amplifies complement cascade activation and protects cells from infection, while it induces low-grade inflammation (LGI) in CVDs." (PMID 39416783, 2024). "The role of CFD in protecting cells from infection has been well recognized." (PMID 39416783, 2024). "In fact, there was a decrease in the mRNA levels of innate-immunity related genes from blood mononuclear cells following intramammary infection with M. bovis, such as complement factor D (CFD), ficolin 1 (FCN1), and tumor necrosis factor superfamily member 13 (TNFSF13)." (PMID 38515536, 2024). "Notably and in contrast to ZIKV, the highest upregulated mRNA during DENV-infection was for the complement alternative pathway activator, complement factor D (CfD)." (PMID 37022660, 2023). "Furthermore, CFD is a modulator of complement activation during infection affecting the innate immune response." (PMID 34396466, 2021). "The complement factor D (CFD) exerts a regulatory role during infection." (PMID 34396466, 2021). "CFD, a member of the trypsin family, activates the alternative pathway by cleaving C3b-bound factor B and is involved in innate and adaptive defences against pathogen infection." (PMID 33933138, 2021). "In contrast, CfD was the highest mRNA induced by DENV, suggesting a more local acting, complement driven response to infection." (PMID 37022660, 2023). "Our KEGG pathway enrichment analysis indicates that the up-regulated DEGs including C3, PLG, CFD, CR1, and C1QB are still enriched in complement and coagulation cascades, up to 24 h after infection." (PMID 31316336, 2019).
metabolic disorders (3 papers, 2024 to 2026). "Here we show that MAT-derived complement factor D (CFD) and component 3 (C3) derived from steatotic liver coordinately drive excessive alternative complement activation, resulting in cartilage damage in mice during aging and metabolic disorders." (PMID 42056078, 2026).
bacterial infections (2 papers, 2021). "We describe two siblings with a heterozygous NM_001928.3(CFD):c.125C>A p.(Ser42*) mutation in the complement factor D (fD) gene having a history of recurrent bacterial infections." (PMID 33841879, 2021). "A high susceptibility to bacterial infections with Neisseria spp. has been observed in complement factor D (CFD) deficient humans." (PMID 34396466, 2021).
kidney disease (2 papers, 2023 to 2024). "In addition, deposition of complement factors CFD and C3c in hearts from NZB/W mice was seen, which correlated with the severity of kidney disease." (PMID 37554366, 2023).
CFD also shares sentences with these, for which no sentence is quoted: coronary heart disease (3 papers); cardiovascular disease (2); cataract (2); cutaneous squamous cell carcinoma (2); Hypertension (2); osteoarthritis (2); AA amyloidosis (1); acquired partial lipodystrophy (1); acute myeloid leukemia (1); angiosarcoma (1); Arrhythmia (1); atherosclerosis (1); autoimmune thyroid disease (1); bladder cancer (1); cardiomyopathy (1); cervical cancer (1); colorectal cancer (1); knee osteoarthritis (1); leukemia (1); Lipedema (1); lymph node metastasis (1); Multiple Myeloma (1); myocardial infarction (1); myopia (1); Neonatal sepsis (1); nephrotic syndrome (1); pancreatic cancer (1); pancreatic ductal adenocarcinoma (1); preeclampsia (1); prostate (1).
A further 7 diseases each share a sentence with CFD in 1 paper.